AR (androgen receptor)
Diseases named in the same sentence as AR in open-access papers (continued):
Sharing a sentence is not in itself a finding about the gene and the disease.
tumor (continued). "Also, as AR is a nuclear hormone receptor, the difference in ligand bioactivity and the ultimate AR function might be regulated in a manner dependent upon tumor stage, tumor microenvironment, as well as a potential expression of its target molecules." (PMID 33783995, 2021). "Furthermore, active STAT5a/b protects antiandrogen-liganded AR from proteasomal degradation, while STAT5a/b knockdown combined with antiandrogen treatment enhances proteasomal degradation of AR followed by suppression of tumor growth." (PMID 34638338, 2021). "Thus, being able to predict AR activity within the tumor via a minimally invasive method may enlighten therapeutic selection." (PMID 34736512, 2021). "Collectively, these results demonstrate that the SQLE inhibitor terbinafine efficiently reduces the growth of PCa orthografts without major systemic toxicity and that inhibition of tumour growth by terbinafine is associated with the induction of apoptosis and reduced AR activity." (PMID 34417456, 2021). "Thus, we hypothesized that the AR and AD effects on tumor growth are DDR independent, a mechanism that remain to be fully described in further studies." (PMID 34203903, 2021). "Therefore, targeting the MLK family may not elicit side effects in normal tissues, but may increase cytotoxic effects in the tumor cells of patients undergoing treatment with either ADT/or AR inhibitors." (PMID 34439974, 2021). "Together these in vitro and in vivo results indicated that loss of AR activity in response to androgen deprivation at AR/MYC co-regulated genes is buffered by an increase in MYC, along with an increase in expression of MYC-unique genes that may further enhance tumor growth." (PMID 34911936, 2021). "Estradiol response down was negatively enriched, and a trend of an increased androgen response was observed (adj P‐value 0.0656) suggesting that ER, PR, and AR function may be closely interconnected in the normal breast epithelium as observed in ER+ tumor cells." (PMID 34042278, 2021). "Hence, the data confirm our hypothesis that the tumor suppressors and AR co-repressors ING1 and ING2 functionally mediate the transrepression of androgen-activated AR on hTERT. * p ≤ 0.05." (PMID 34439179, 2021). "Consequently, AR mutations are responsible for the continuous activation of the receptor even in the presence of low circulating androgen levels after ADT therapy, thus playing a key role in tumor progression." (PMID 34067217, 2021). "We hypothesize that high levels of SRD5A1 mRNA in SDC tissue are indicative of a high dependency on AR signaling for tumor proliferation, as well as that the deprivation of circulating androgens will hit these tumors hard, resulting in a better prognosis upon CAB treatment." (PMID 34298742, 2021). "In this study, we have investigated the role of AR by evaluating the AR/ER ratio specifically in patients younger than 50 years of age and who are likely to have a dominant estrogenic environment and the role of this particular hormonal environment on tumor progression." (PMID 34234742, 2021). "Notably, after each therapeutic resistance stage from localized CSPCa to metastatic CRPCa, it seems that the tumor becomes more aggressive through activated adaptive responses, relies more on those alternative pathways, and becomes less dependent on AR signaling." (PMID 34681745, 2021). "Thus, the nuclear localization of AR in tumor cells indicates an active AR signaling status." (PMID 33448107, 2021). "Furthermore, our data identified a negative association between relaxin expression and tumor growth and a significant positive correlation between relaxin expression and AR expression (r = 0.67, * p ≤ 0.002) in the male cohort." (PMID 34440475, 2021). "Indeed, analysis of AR gain in circulating tumor DNA and AR-V7 in exosomes, in conjunction with standard clinical assessment, may help identifying men who will not benefit from abiraterone or enzalutamide therapy." (PMID 33500577, 2021).
tumor (continued). "Taken together, serum levels of these candidate proteins may reflect tumor AR activity." (PMID 34736512, 2021). "In addition, compared with the primary tumor, AR gene expression increased in circulating tumor cells and early lung metastases, indicating that AR may promote the spread of metastasis by supporting the survival of BC cells during metastasis." (PMID 32982970, 2020). "Interestingly, both AR antagonists and androgens at SAL can trigger cellular senescence in PCa in cell culture and ex vivo tumor samples, which might be one of the underlying mechanisms of AR ligand-mediated PCa growth inhibition." (PMID 32650419, 2020). "AR positivity was associated with poorer outcomes in ER negative tumours." (PMID 32928183, 2020). "However, the presence of AR in the positive MMP-2 in tumor epithelium reduced survival in patients." (PMID 32718331, 2020). "Analysis of the associations between AR protein expression and clinical features in patients with PTC showed that a trend of reduced AR protein expression tended to be associated with advanced tumor characteristics, including higher tumor stage, extrathyroidal extension and lymph node metastasis." (PMID 32365531, 2020). "The AR isoform splice variant 7 (AR-V7) results in a truncated receptor that lacks the binding site for androgen, activated even in the absence of ligands and stimulating tumor growth." (PMID 33194707, 2020). "Recent studies on T-NEPC had shown that AR often positively expressed in tumor cells, but despite the AR protein expression in the nucleus, the transcriptional activity of AR was very low, which indicated that epigenetic mechanisms may inhibit AR function." (PMID 33598420, 2020). "Furthermore, they found an increase in growth inhibition of relapsed tumours when higher doses of testosterone were used, indicating that the manipulation of the androgen/AR signalling pathway in AR-positive metastatic PC may be a potential therapy target." (PMID 33303035, 2020). "Additionally, curcumin inhibits multiple growth tumor through inhibiting AR expression." (PMID 31896509, 2020). "The inverse association between MEIS1 expression and AR extended further to HOXB13 expression, indicating that in a subset of primary PCa, decreased expression of MEIS1 may be necessary for AR and HOXB13 to drive tumor development and progression." (PMID 32681068, 2020). "Collectively, these results suggest that for AR negative AKR1C2 positive (AR−/AKR1C2+) ESCC, AKR1C2 mediates activation of PI3K/AKT pathway may be an alternative to DHT‐AR pathway, which uses androgen metabolites to activate a classic tumour signalling pathway." (PMID 32678482, 2020). "Apalutamide, an oral non-steroidal, second-generation, selective inhibitor of the androgen receptor (AR), binds directly to the ligand-binding domain of the AR, thereby preventing AR nuclear translocation and AR-mediated transcription, which in turn induces tumour cell death." (PMID 32878613, 2020). "Therefore, the ability of a tumor to produce its own androgens, as well as its reliance on splice variants may also play an important role in understanding how AR is functioning to drive tumor growth in the context of ADT or antiandrogen therapies." (PMID 33062889, 2020). "This wide variation in AR expression could be due to differences in tumour biology." (PMID 32928183, 2020). "Using relative transcriptional levels of novel biomarkers under investigation such as PSMA and AR in liquid biopsies from patients with mCRPC prior to 177Lu-PSMA-therapy, this study points at a relation of the molecular diagnostic CTC footprint to tumor load measured by PSMA-PET-CT imaging." (PMID 32685010, 2020). "In addition, although AR expression was nearly negative in B45354 tumor tissues, an increase in the levels of the androgen receptor variant 7 (ARV7) was detected in the PDX tissue by RT-PCR, but weak positive expression was detected by IHC." (PMID 32092044, 2020).
tumor (continued). "In addition to tumor cells, IL-1 also is produced by myeloid precursor cells, macrophages, and neutrophils in the tumor microenvironment; and our published data indicate that bone marrow stromal cell IL-1 paracrine signaling represses AR levels and activity in PCa cells." (PMID 33326447, 2020). "Thus, AR can clearly play both tumor-suppressing and oncogenic roles in BC." (PMID 32373367, 2020). "Moreover, we can speculate that the engraftment of androgen-dependent TNBC may be compromised in female nude mice, in which androgen production may be insufficient to support AR-dependent tumor growth." (PMID 32042320, 2020). "Furthermore, AR expression was obviously decreased in tumor area by ALZ003 administration." (PMID 31896509, 2020). "However, whether the tumor response to the inhibitors is solely dependent on suppressing AR signaling remains unclear." (PMID 31428587, 2019). "However, all AR splice variants are not tumor-specific, making CTCs a more accurate source for disease prognostication, especially in low-volume disease." (PMID 31877738, 2019). "In addition AR inhibition attenuates tumor growth of T24 xenografts." (PMID 31119584, 2019). "Blocking activation of the androgen receptor (AR) signaling pathway by ADT is highly effective in reducing PCa tumor growth; however, preclinical studies and clinical trials were not able to assess whether the addition of ADT to EBRT induces a synergistic or additive effect." (PMID 31635359, 2019). "In addition, we assessed whether the difference in the AR/ER and AR/PgR ratios between primary tumor and metastasis influenced prognosis." (PMID 31110518, 2019). "In this study, we investigated whether sPSA might reflect tumor biology, including AR signaling." (PMID 31664946, 2019). "Moreover, abiraterone alone was not shown to be effective at reducing other mechanisms of tumor resistance such as reducing AR splice variant expression." (PMID 31771198, 2019). "To dissect the mechanisms underlying AR’s promotion of RCC cell proliferation, we focused on the ASS1, as recent studies have indicated that decreased ASS1 activity might lead to an increase in the tumor growth." (PMID 31000693, 2019). "Indeed, AR, a ligand-activated intracellular transcription factor belonging to the steroid hormone receptor family, currently represents the main validated drug target in the management and progression of this neoplastic disease." (PMID 31616657, 2019). "There is abundant evidence from tumor sequencing studies that genomic alterations in AR (amplification and/or mutation) are present in over 50% of CRPC patients and that AR amplification is associated with a less favorable clinical response to abiraterone or enzalutamide treatment." (PMID 30644358, 2019). "Thus targeting instead the FABP5- PPARγ-VEGF axis, which we suggest, gradually replaces the AR-mediated signalling pathway in tumour progression, could be an alternative way for treatment of CRPC." (PMID 31258834, 2019). "BEZ235 was also reported to reduce tumor volume in a mouse model harboring PTEN loss, and the effects were enhanced when combined with AR antagonist enzalutamide, implying a potential prospect in synergy treatments cotargeting the AR, PI3K and mTOR signaling pathways in PCa." (PMID 30754640, 2019). "It is possible that tumor clones with the AR aberrations regressed dramatically by exposure to enzalutamide, and the tumor may have eventually acquired resistance to enzalutamide by other mechanisms such as increased de novo steroidogenesis through overexpression or mutation of HSD3B122." (PMID 30858508, 2019).
tumor (continued). "In addition, after enzalutamide or abiraterone treatment, the tumor can progress with more aggressive variants characterized by a reduced or absent AR expression and histological features of neuroendocrine differentiation." (PMID 30642011, 2019). "Heterogeneity in AR expression in CRPC tends to become accentuated such that AR+ PCa cells may evolve into AR+/hi cells and the AR-/lo cell population may expand, leading to co-evolution of both subpopulation of PCa cells in the primary (prostate) tumor." (PMID 30190514, 2018). "Moreover, we have investigated the ability of these cytokines to induce in PCa cells the production of factors promoting tumor progression through the inhibition of adaptive immune responses and/or the activation of alternative pathways for the androgen receptor." (PMID 29896191, 2018). "Our finding that AR deletion results in failure of tumor formation following Pten inactivation could be due to differences between CARNs and bulk luminal cells and/or to differences due to Pten loss in the regressed versus hormonally intact prostate epithelium." (PMID 29334357, 2018). "However, treatment failure following such anti-androgen therapies is frequently associated with the appearance of AR-negative tumor cells, which are typically associated with highly aggressive lethal disease." (PMID 29334357, 2018). "During tumor progression, selection for cells that express AR-Vs could occur, via selection of more malignant or castration-resistant subclones or even via the hormone-dependant regulation of AR isoforms." (PMID 30028845, 2018). "However, subsets of tumor cells develop resistance in hypoxia because they are more capable of adaptively responding to androgen/AR-blockade in the hypoxic condition, becoming androgen/AR-independent, or conditionally (hypoxic) androgen/AR-independent." (PMID 30478344, 2018). "Therefore, the current study specifically investigated bone cell activity in clinical bone metastases in relation to tumor cell AR activity, in order to gain novel insight into biological heterogeneities of possible importance for patient stratification into bone-targeting therapies." (PMID 29670000, 2018). "While enzalutamide blocks the ligand-binding domain of AR and thus prevents the binding of its natural androgen ligands, abiraterone inhibits cytochrome P450 17A1, which is required for adrenal and intratumoral androgen production, and therefore suppresses the androgen level in the tumor." (PMID 29682197, 2018). "Although CARNs express AR, it has been unclear whether AR is required for any or all the progenitor properties of CARNs, and whether the intrinsic castration-resistance of untransformed CARNs might resemble the castration-resistance of tumor cells in CRPC." (PMID 29334357, 2018). "Early immunohistochemical studies reveal that tumor tissues generally exhibit lower AR expression than normal and benign hyperplastic tissues, and also high Gleason score or less differentiated cancers display lower AR expression than low Gleason score cancers." (PMID 29555975, 2018). "Galeterone has shown significant anti-tumour activity with a well-tolerated safety profile in patients with CRPC in phase I and II clinical studies including in six out of seven Phase II patients who were identified in a retrospective subset analysis as having truncated AR with C-terminal loss." (PMID 29861848, 2018). "We found that the tumor tissues with high level of AR-v7 also expressed higher level of XPO1, suggesting that there could be a molecular interaction between XPO1 and AR splice variants." (PMID 30450161, 2018). "Further, the use of tumor genomic expression profiling and the detection of patient AR response biomarkers may be very important in selecting appropriate patients for anti-androgen therapeutics, monitoring the bioactivity of new drug candidates, and predicting therapy outcomes and adverse events." (PMID 27741511, 2017).
tumor (continued). "Other groups have found that AR may mediate tumor growth through activating HIF-2α/VEGF-signaling." (PMID 28085048, 2017). "Interestingly, tumor cells in this model commonly lose androgen receptor expression." (PMID 29113300, 2017). "The association between AR expression and prognosis in patients with MI tumor could not be analyzed because only one study demonstrated such data." (PMID 28362839, 2017). "The authors concluded that AR might function as a tumor suppressor in this context." (PMID 28085048, 2017). "Full activation of the AR receptor as shown by AR-515 plus total AR significantly associated with increased lymphovascular invasion (p = 0.033), lower KM grade (p = 0.004), increased tumour-stroma percentage (TSP) (p = 0.033) and increased tumour budding (p = 0.007)." (PMID 28415597, 2017). "By analyzing tumor biopsy mRNA from CRPC patients who had developed resistance to CYP17 inhibitor treatment, we have identified a novel nonsense mutation (Q784*) at the ligand binding domain (LBD) of AR, which produces a C-terminal truncated AR protein that lacks intact LBD." (PMID 28036278, 2017). "However, increasing tumor AR expression with advancing age may indicate a link with the hepatitis B virus given evidence of a positive feedback loop with AR signaling." (PMID 29254188, 2017). "Additionally, the ratio of nuclear AR to total AR was positively related to tumor grade." (PMID 27848972, 2016). "However, co-culture with PrSC did not induce the expression of MYC in these cells, suggesting that elevated MYC in NHPrE1/AR tissue recombinants may result from the presence of other cellular components in the tumor microenvironment." (PMID 27611945, 2016). "Whether AR has tumor suppressor or promoter activity in RCC has clinical implications." (PMID 26814892, 2016). "However, one of the most intriguing ways for AR dependency of the tumor even in complete absence of ligand is the increased expression of many AR splice variants (AR-Vs) which can be constitutively nuclear and transcriptionally active, and lack the LBD." (PMID 26918604, 2016). "Given the apparent induction of Snail by AR and vice versa, one could envision a scenario in which either of these factors initiates gene changes that feed into the other, thereby leading to an aggressive, treatment-resistant tumor." (PMID 27409172, 2016). "Thus, patients with AR-positive tumor had a significantly lower risk of BC recurrence (P=0.031), compared with those with AR-negative tumor." (PMID 26885620, 2016). "Thus, inhibiting SIAH2 may also enhance EAF2 tumor suppressive activity, in addition to inhibiting castration-resistant AR activation." (PMID 27058417, 2016). "Furthermore, it appears that AR status is highly preserved during tumor progression but discordance between primary and metastatic sites may occur in a small fraction of tumors." (PMID 26552477, 2015). "Importantly, the failure of androgen deprivation therapy is not accompanied by the loss of androgen receptor (AR) expression or transcriptional activity, and AR activity remains critical for tumor growth in CRPC." (PMID 26636648, 2015). "Thus, the cellular context in which miR-375 may act as oncomiR or tumor suppressor is likely to be conditioned by androgen receptor regulation." (PMID 25977730, 2015). "Genetic alterations such as AR gene amplification resulting in increased AR expression occur in about one third of CRPC tumors, while AR mutation or alternative splice variants allowing the tumor to respond to very low androgen levels can be observed in a smaller subset of CRPC cases." (PMID 26325261, 2015). "Finally, the tumor suppressing activity of AR in some EC cell lines and studies might limit its usefulness as a predictor of outcome." (PMID 26397136, 2015).